LPL (lipoprotein lipase)
Diseases named in the same sentence as LPL in open-access papers (continued):
Sharing a sentence is not in itself a finding about the gene and the disease.
hepatoma (11 papers, 2011 to 2025). "Further evidence that LPL is a poor prognostic indicator for human hepatocellular carcinoma comes from the association of high levels of LPL with aggressive tumor morphologies and patient short-term survival." (PMID 38339301, 2024). "We previously showed that exogenously added LPL increases HCV binding to hepatoma cells by acting as a bridge between virus-associated lipoproteins and cell surface heparan sulfate, while simultaneously decreasing infection levels." (PMID 22039521, 2011). "Further, elevated LPL and CERS5/6 expression are significantly associated with reduced survival in hepatocellular carcinoma." (PMID 41256541, 2025). "Previous research has demonstrated that blocking LPL prevented a variety of hepatoma cells from proliferating." (PMID 38339301, 2024). "IGF-1 has an inhibitory effect on lipolytic enzyme lipoprotein lipase which prevents the virus cell entry in hepatoma cells." (PMID 36374927, 2022). "The influence of LPL on HCV infection in vitro was further evaluated by the group of Budkowska, which showed that LPL-treated hepatoma cells were less permissive to serum HCV infection, in spite of a higher yield of particle binding and internalization." (PMID 24278733, 2012). "We performed a series of control experiments to assess the impact of LPL on lipoprotein metabolism in hepatoma cells." (PMID 22039521, 2011). "This “molecular bridging” of HCV to hepatoma cells was mediated by the dimeric form of LPL and was analogous to the mechanism by which the liver takes up lipoproteins from the bloodstream." (PMID 22039521, 2011). "We show here that LPL efficiently inhibits cell infection with two HCV strains produced in hepatoma cells or in primary human hepatocytes transplanted into uPA-SCID mice with fully functional human ApoB-lipoprotein profiles." (PMID 22039521, 2011). "Interestingly, in vitro the addition of LPL increases HCV binding to hepatoma cells presumably through the effect of LPL on maintaining HCV at the cell surface, thus inhibiting uptake." (PMID 38455763, 2024). "Thus, exogenously added LPL has a potent inhibitory effect on cell infection with HCV produced in hepatoma cells in vitro or in vivo in human primary hepatocytes transplanted into chimeric mice." (PMID 22039521, 2011). "We show here that LPL inhibits cell infection with two strains of HCV, JFH-1 and J6/JFH-1, which replicate in hepatoma cells in vitro." (PMID 22039521, 2011). "In a previous study, we showed that LPL enhances the binding of HCV from the sera of patients to various cell types, including hepatoma cell lines." (PMID 22039521, 2011). "The latest research revealed that LPL/FABP4/CPT1, a fatty acid metabolism reprogramming axis, was significantly upregulated in nonalcoholic steatohepatitis (NASH) and cooperated with a large number of oncogenic signals to drive NASH to directly progress to hepatocellular carcinoma." (PMID 36254139, 2022).
myocardial infarction (11 papers, 2010 to 2026). Gross necrosis of the myocardium, as a result of interruption of the blood supply to the area, as in coronary thrombosis. "They found a significant association between myocardial infarction and lipid metabolism-related gene variants, such as lipoprotein lipase (LPL), apolipoprotein E (APOE) and proprotein convertase subtilisin/kexin type 9 (PCSK9), as well as eNOS gene variants." (PMID 34564134, 2021). "The LPL 447X genotype has been consistently associated in adult populations with a beneficial lipid profile conferring a protective effect against myocardial infarction." (PMID 19403283, 2010). "As intramuscular TG accumulation is predominantly regulated by the action of HSL and LPL, the contribution of cardiac LPL to the altered lipid accumulation and the cardioprotective phenotype of Gipr−/− mice following myocardial infarction would be interesting to study." (PMID 39081272, 2024). "The SNP rs7011846, located approximately 26 kb upstream of LPL and identified as a lead SNP for myocardial infarction is one of relatively few SNPs in our study which changes one ATF4 binding motif to another, rather than creating or disrupting a binding motif." (PMID 37906604, 2023). "The SNP rs7011846 (intergenic, upstream of LPL; ATTGC[G/A]TCAC) is a GWAS lead SNP for myocardial infarction (MI) and resides in a macrophage- and adipose-specific open chromatin region." (PMID 37906604, 2023).
prostate cancer (11 papers, 2009 to 2025). A primary or metastatic malignant tumor involving the prostate gland. "For example, Narita and colleagues reported a significant association between increased hydrolytic activity of LPL due to the LPL polymorphism (Ser447stop) and the susceptibility to prostate cancer." (PMID 25866768, 2015). "Importantly, they also found low LPL expression in all prostate cancer cell lines, which they explained with the frequent loss of the LPL locus due to a nearby tumor suppressor gene, however, without naming NKX3.1." (PMID 40563400, 2025). "Moreover, an LPL Ser447stop polymorphism has been shown to be associated with prostate cancer risk and the LPL gene is commonly methylated in prostate tumors." (PMID 22028972, 2012). "Wilson and colleagues identified amplified genes implicated in steroid biosynthesis and lipid metabolism, including but not limited to 17β-HSD and lipoprotein lipase (LPL) in androgen-insensitive prostate cancer cell lines." (PMID 40269952, 2025). "Considering the importance of lipid metabolism for steroidogenesis and cancer growth, enhanced expression of LPL has been reported in advanced prostate cancer cell lines." (PMID 40563400, 2025). "An established cytogenetic probe against the LPL locus has been repeatedly used in prostate cancer research." (PMID 40563400, 2025). "This study aims to demonstrate that deletion of the LPL gene, frequently mentioned in prostate cancer research, occurs incidentally alongside the tumor suppressor NKX3.1, a well-known event in prostate carcinogenesis." (PMID 40563400, 2025). "Other targets that have been associated with prostate cancer metastasis (or progression) include BIRC5/survivin, EZH2, TOP2A, HMMR, LPL, and SSTR1." (PMID 34680307, 2021). "LPL expression in other tumors, such as liposarcoma and prostate cancer, also indicates that the metabolic machineries for both lipogenesis and lipolysis are widely co-expressed in cancers of diverse origins." (PMID 25215509, 2014). "It has been found that deletion of LPL is observed in 68% (52/76) of localized prostate cancers by FISH analysis." (PMID 22028972, 2012). "While 8p21.3 deletion was associated with a poor Gleason score, it was not linked to NKX3.1 or LPL expression in our prostate cancer cohort." (PMID 40563400, 2025). "Furthermore, studies have demonstrated the role of LPL expression and phosphorylation in prostate cancer cells on invasion in vitro and tumor growth and metastasis in vivo in a mouse model." (PMID 34572081, 2021). "Furthermore, results obtained with a mouse model have shown that metastasis of prostate cancer is diminished when LPL expression is reduced, while increased LPL expression levels and its phosphorylation give rise to increased metastasis." (PMID 28145401, 2017). "In the context of prostate cancer, increased LPL activity may promote tumor cell growth." (PMID 40563400, 2025). "In this study, we tested LPL, MYC, PTEN, CEP 7, CEP 8, and CEP 10 FISH probes, based on the published roles of these genes, and on our initial FISH study on FFPE prostate cancer and BPH specimens." (PMID 24568597, 2014). "We analyzed 28 formalin-fixed paraffin-embedded prostate cancer samples with confirmed LPL deletion and 28 without." (PMID 40563400, 2025). "We analyzed a cohort of prostate cancer patients examined by FISH between 2007 and 2017, consisting of 28 patients with confirmed LPL (8p21.3) deletion and 28 patients without this aberration." (PMID 40563400, 2025).
Abdominal obesity (10 papers, 2009 to 2025). Excessive fat around the stomach and abdomen. "Statistically significant association was observed between LPL P+/- polymorphism and abdominal obesity." (PMID 19804633, 2009). "Reduced testosterone levels increase lipoprotein lipase activity and stimulate pluripotent stem cells to differentiate into adipocytes, thereby promoting triglyceride storage and exacerbating central obesity." (PMID 41457293, 2025). "Moreover, rs328 polymorphism in the G allele of LPL could reduce the risk of abdominal obesity." (PMID 37697333, 2023). "Abdominal obesity was correlated to LPL P+/-, P+/+ genotypes (p = 0.013; df = 2; X2 = 7.794) in a significant manner." (PMID 19804633, 2009). "We conclude that a diet low in SFA might help reduce the genetic risk of central obesity confirmed by CETP and LPL genetic variants." (PMID 35807893, 2022). "MDA was the variable that was most positively associated with the estimated LDL-C levels in all multivariate models composed of variables associated with LPL, ADRB3 and MTHFR gene methylation levels, oxidative stress, inflammation, abdominal obesity, food intake and epidemiological variables." (PMID 33326437, 2020). "Increased muscle insulin sensitivity, lipoprotein lipase activity in active musculoskeletal, transport of lipids and lipoproteins from the peripheral blood circulation and tissues to the liver, and reduction abdominal obesity are mechanisms by which MetS may improve with fitness." (PMID 33849567, 2021).
lymphoplasmacytic lymphoma (10 papers, 2018 to 2024). A clonal neoplasm of small B-lymphocytes, lymphoplasmacytoid cells, and plasma cells involving the bone marrow, lymph nodes, and the spleen. "Prevalent MUM-1 immunoreaction alone was considered diagnostic for plasmacytoid differentiation (lymphoplasmacytic lymphoma = LPL)." (PMID 36157173, 2022). "68Ga-pentixafor PET/CT was reported to have a high sensitivity in detecting tumor involvement of Waldenström macroglobulinemia/lymphoplasmacytic lymphoma (WM/LPL) in our previous study." (PMID 34714390, 2021). "Since 2016, testing for MyD88 was added to the essential recommendations for initial work-up of lymphoplasmacytic lymphoma/Waldenstrom’s macroglobulinemia (LPL/WM) in the National Comprehensive Cancer Network (NCCN) Guidelines." (PMID 30583727, 2018). "Using the Surveillance, Epidemiology, and End Results-17 database, we conducted a population-based study of adult patients with transformed follicular lymphoma (t-FL), marginal zone lymphoma (t-MZL), lymphoplasmacytic lymphoma/Waldenström macroglobulinemia (t-LPL/WM), and de novo DLBCL." (PMID 39609401, 2024). "MYD88 Leu252Pro (formerly Leu265Pro) mutations are particularly related to lymphoplasmacytic lymphoma/Waldenström macroglobulinemia (LPL/WM), which would not be expected to have a substantial bloodborne component." (PMID 37932435, 2023).
cardiomyopathy (9 papers, 2007 to 2025). A disease of the heart muscle or myocardium proper. "Cardiac-restricted overexpression of ANGPTL4 in mouse model significantly inhibits cardiac LPL activity and results in cardiomyopathy." (PMID 34616362, 2021). "For example, overexpression of LpL or PPARγ in hearts induced lipotoxic cardiomyopathy phenotypes including ectopic cardiac lipid accumulation and dilated cardiomyopathy." (PMID 30485307, 2018). "Furthermore, a new model of cardiomyopathy was created due to the excessive myocardial uptake of TAG via LPL action, suggesting that cardiomyocyte cell surface LPL is physiologically functional in terms of mediation of cardiac TAG uptake." (PMID 21773049, 2011). "Transgenic mice with Angptl4 overexpression directed to heart muscle (lipoprotein-derived fatty acids are the major energy source in this tissue) show reduced cardiac LPL activity, decreased triglyceride utilization and impaired cardiac function resulting in cardiomyopathy." (PMID 17949489, 2007). "In addition, decreased expression of lipoprotein lipase (LpL) on the surface of myocardial cells affects the uptake of fatty acids by myocardial cells, whereas overexpression of LpL increases the uptake of fatty acids and leads to cardiomyopathy." (PMID 40478315, 2025). "Accumulation of lipids in cardiomyocytes, through overexpression of long-chain acyl-CoA synthase (ACS) or lipoprotein-lipase (LPL) or inhibition of fatty acid oxidation, induces cardiomyopathy." (PMID 19317897, 2009).
liver fibrosis (9 papers, 2020 to 2025). "Interestingly, the predicted target gene of rs1441754, LPL, is upregulated in hepatic stellate cells and exacerbates liver fibrosis in MASLD in mouse models." (PMID 41282202, 2025). "The hepatic stellate cells (HSC) activation pathway mediated by LPL could be targeted for treating liver fibrosis in patients with NASH." (PMID 37697333, 2023). "The upregulation of LPL has been reported to exacerbate liver fibrosis." (PMID 34248683, 2021). "MF2 cells specifically expressed liver fibrosis-related genes AGTR1, CYGB, PIEZO2, and LPL, and MF5 cells specifically highly expressed immune-related genes TRAC, CD3D, GZMB, and FCGR3A." (PMID 40949143, 2025). "The enhanced mRNA level of LPL in hepatic stellate cells increases the uptake of cholesterol from serum lipoproteins, which induces an increase in TLR4 signaling and the exacerbation of liver fibrosis." (PMID 35369079, 2022).
lung carcinoma (9 papers, 2013 to 2025). "Associations of APOB, APOC3, and HMGCR inhibition and the LPL agonist with distinct lung cancer risks underscore the multifaceted nature of these relationships." (PMID 38034491, 2023). "Associations of APOB, APOC3, and HMGCR inhibition and LPL agonist with distinct lung cancer risks underscore the multifaceted nature of these relationships." (PMID 38034491, 2023). "Analyses of clinical data showed that LPL in lung cancer tissues has considerable diagnostic value for LUAD, and elevated LPL levels were positively associated with improved patient survival outcomes." (PMID 40427755, 2025). "Cell experiments with an LPL activator proved these findings; the activator inhibited the proliferation and migration of lung cancer cells." (PMID 40427755, 2025). "In this drug-target MR analysis, we assessed the effects of LLDs on lung cancer risk via six LLD targets (APOB, APOC3, HMGCR, LPL, NPC1L1, and PCSK9), comprising 12 lipid-lowering pathways." (PMID 38034491, 2023). "We found known lung cancer drivers such as Lipoprotein Lipase (LPL) and CC Chemokine Receptor 2 (CCL2)." (PMID 31640282, 2019). "Several studies have shown that LPL plays an important role in carcinogenesis, including colorectal and pancreatic cancers, and lung cancer." (PMID 23510199, 2013). "The findings suggest that LPL functions as an indicator for predicting both cancer immunotherapy responses and the efficacy of small-molecule drugs targeting this protein, providing strong evidence to further lung cancer treatment research." (PMID 40427755, 2025). "ACADL, CD36, LPL, and MMP1 were the signature genes in the PPAR pathway that were identified to be shared among IPF and lung cancer." (PMID 33046043, 2020). "Meta-analysis of 6 hub genes of lung cancer was performed by ONCOMINE databases, and showed that UGT1A6 and DGAT1 were upregulated, while HPGDS and LPL were downregulated." (PMID 33050938, 2020). "Although the underlying mechanisms on how the most sedentary individuals might have an increased risk of lung cancer are unclear, animal studies showed that lack of activities might suppress lipoprotein lipase activity in skeletal muscles and reduce glucose uptake." (PMID 30859092, 2019). "LPL, which was downregulated in this study, was found to have decreased expression but increased activity in lung cancer tissue compared with adjacent noncancer lung tissue." (PMID 33046043, 2020). "Among the four mutually exclusive genes identified in this study, PPAP2C and LPL were significant in NSCLC, suggesting their involvement in lung cancer but not in IPF." (PMID 33046043, 2020).
non-alcoholic fatty liver disease (9 papers, 2015 to 2025). "Hence, the roles of those overlapping microbes associated with SREBF1 and LPL that also exhibit abnormal abundance in non-alcoholic fatty liver disease merit further investigations." (PMID 33293650, 2020). "For example, microbes with differential abundance in non-alcoholic fatty liver disease (NAFLD) are significantly enriched for SREBF1 and LPL genes via literature-based associations." (PMID 33293650, 2020).
endothelial dysfunction (8 papers, 2015 to 2025). In vascular diseases, endothelial dysfunction is a systemic pathological state of the endothelium (the inner lining of blood vessels) and can be broadly defined as an imbalance between vasodilating and vasoconstricting substances produced by (or acting on) the endothelium. "In addition, leptin promotes the production of proliferative and inflammatory cytokines, it increases platelet aggregation and enhances the secretion of pro-atherogenic lipoprotein lipase by cultured human and rodent macrophages causing endothelial dysfunction by increasing ROS." (PMID 25573199, 2015). "Moreover, the reduced activity of LPL contributes to developing pro-atherogenic lipoproteins such as VLDL and IDL, whose levels are increased in T2D and have been linked to endothelial dysfunction and plaque formation in arteries." (PMID 41373652, 2025). "Cluster 1 (rapidly increasing TyG) likely reflects progressive dysregulation of LPL-mediated triglyceride clearance or elevated ANGPTL3/4/8 expression, promoting atherogenic lipoprotein accumulation and endothelial dysfunction." (PMID 41585791, 2025).
liver cancer (8 papers, 2019 to 2024). An epithelial or non-epithelial malignant neoplasm that arises from the liver. "The development of non-alcoholic steatohepatitis into liver cancer was substantially prevented by targeted suppression of LPL-mediated fatty acid metabolism." (PMID 38339301, 2024). "A recent study suggested that targeted inhibition of LPL/FABP4/CPT1 fatty acid metabolic axis can effectively prevent the progression of nonalcoholic steatohepatitis to liver cancer." (PMID 37950277, 2023). "In particular, Orlistat is most obvious, possibly because LPL is at the beginning of the process of breaking down chylous droplets absorbed by the liver, providing fatty acid for the proliferation of liver cancer cells." (PMID 34803493, 2021). "Microsphere formation and clonal formation assays in vitro were applied to study if inhibition of the LPL/FABP4/CPT1 axis can reduce the viability of liver cancer stem cells (LCSCs)." (PMID 34803493, 2021). "Consequently, a potential therapeutic for inhibiting the proliferation of liver cancer cells involves targeting LPL." (PMID 38339301, 2024). "Liver cancer cells are more likely to take up and use fatty acids when LPL expression is higher." (PMID 38791477, 2024). "Similarly, a previous study demonstrated that inhibition of the LPL/FABP4/CPT1 axis can effectively prevent the progression of NASH to liver cancer." (PMID 38388533, 2024). "Although activation of the LPL/FABP4/CPT1 metabolic axis may be beneficial for the maintenance of liver cancer stem cells (LCSCs), the genesis of TICs should involve more complex mechanisms that require the malignant transformation of normal hepatocytes." (PMID 34803493, 2021). "Therefore, the synergistic upregulation of the LPL/FABP4/CPT1 molecules in the NASH stage may accelerate the occurrence of liver cancer by nourishing the TICs formation." (PMID 34803493, 2021). "Although no experimental data pertaining to AGAP11 have been reported in the field of cancer, there is evidence to suggest that closely related genes, namely, LPL, MMP9, SGK1, TLR4, and FOS play certain roles in liver cancer through different mechanisms." (PMID 36726348, 2023).